FMR1 (fragile X messenger ribonucleoprotein 1)
Diseases named in the same sentence as FMR1 in open-access papers (continued):
Sharing a sentence is not in itself a finding about the gene and the disease.
Intellectual disability (continued). "This gene has previously been implicated in intellectual disability and is apparently linked to FMR1 and NEFH overexpression associated with neurological disorders." (PMID 30567555, 2018). "This syndrome is a type of inherited intellectual disability caused by a mutation of the fragile X mental retardation 1 (fmr1) gene on the X chromosome." (PMID 28632163, 2017). "The fragile X mental retardation (FMR1) gene encodes an RNA-binding protein that plays a role in intracellular RNA transport and in the regulation of translation of target mRNAs." (PMID 29253856, 2017). "Briefly, FXS is a common inherited cause of mental retardation, human cognitive dysfunction, and autism resulting from the transcriptional silencing of the FMR1 gene that encodes FMRP." (PMID 28331639, 2017). "FXS, an X-linked dominant neurodevelopmental syndrome characterized by moderate to severe mental retardation, macroorchidism and distinctive facial anomalies, is caused by loss of the protein-synthesis inhibitor FMR1 (fragile X mental retardation)." (PMID 26935104, 2016). "Validated targets of miR-146a include MAP1B, which regulates AMPA receptor endocytosis, while direct targets of miR-221 include FMR1, the fragile X gene which is the most frequent cause of syndromic intellectual disability (ID) and ASD." (PMID 26753090, 2016). "FXTAS is a late onset X linked genetic cause of mental retardation and autism due to trinucleotide repeat mutation of the Fragile X Mental Retardation 1 (FMR1) gene, and is commonly seen in males between the ages of 50 and80 years." (PMID 26206249, 2015). "The Fragile X (FraX) family of RNA binding proteins is most commonly studied in the context of neurological disorders, as mutations in Fragile X Mental Retardation 1 (FMR1) are the leading cause of inherited mental retardation." (PMID 26571124, 2015). "The FMR1 allele with the G-insertion mutation was identified in a male patient with moderate to severe intellectual disability, first seen at the age of 36 years in a residential care setting (Fig1B)." (PMID 25693964, 2015). "Fragile X syndrome (FXS), the leading cause of inherited intellectual disability, is caused by epigenetic silencing of the FMR1 gene, through expansion and methylation of a CGG triplet repeat (methylated full mutation)." (PMID 23874213, 2013). "The FMR1 full mutation can cause a broad spectrum of involvement, including intellectual disability, behavior problems, social deficits and autism spectrum disorders (ASD)." (PMID 23259642, 2012). "Therefore, having an FMR1 full mutation entails a risk for intellectual disability that is 50–300 times higher than the risk in the general population." (PMID 35719251, 2022). "The fragile X syndrome (FXS) is an X-chromosome-linked neurodevelopmental disorder with severe intellectual disability caused by inactivation of the fragile X mental retardation 1 (FMR1) gene and subsequent loss of the fragile X mental retardation protein (FMRP)." (PMID 34205274, 2021). "Moreover, it dysregulated other genes linked to intellectual disability, such as FMR1, SYN1, CAMK2A, and THOC2." (PMID 34946860, 2021). "Fragile X syndrome (FXS) is the most common inherited cause of mental retardation, resulted from the transcriptional silencing of the fragile X mental retardation 1 (Fmr1) gene and the subsequent loss of fragile X mental retardation protein (FMRP; Davis and Broadie, 2017)." (PMID 31882402, 2020). "Mutations in the human FMRP-coding gene (Fmr1) are associated with neurodevelopmental disorders, such as fragile X mental retardation, a disease characterized by intellectual disability, disruptive and autistic-like behavior, epileptic seizures and language deficits, and autism." (PMID 24679524, 2014).
Intellectual disability (continued). "In conclusion, laboratories performing molecular genetic studies of idiopathic intellectual disability would benefit from the implementation of this methodology, which enables a widened scope of detection of the mutational hotspot regions of FMR1, AFF2 and ARX genes in a single initial assay." (PMID 23914978, 2013). "The absence or reduction of FMR1 leads to unbalanced neuronal circuits, which manifests as intellectual disability, hyperactivity, autism spectrum disorder, impulsivity, and language development issues." (PMID 40062023, 2025). "The name for the FMR1 gene is currently known as “fragile X messenger ribonucleoprotein-1” gene, replacing the old name “fragile X mental retardation-1” in 2022." (PMID 40821284, 2025). "The identification of the FMR1 gene mutation in 1991 marked a pivotal breakthrough, establishing FXS as the most common inherited cause of intellectual disability and a leading monogenic contributor to autism spectrum disorder." (PMID 40299377, 2025). "Additional genetic investigations for neurodevelopmental troubles have been performed using an array CGH in 37% (79 of 214), an intellectual disability panel in 7.4% (16 of 216), and a dedicated test for FMR1 in 12.5%." (PMID 40822950, 2025). "FXS is the common inherited cause of intellectual disability and ASD, typically resulting from the transcriptional silencing of fragile X mental retardation type 1 (Fmr1) on the X chromosome and loss of the encoded protein, FMRP." (PMID 37445914, 2023). "For example, human orthologs to fly genes CASK (CASK), Mnb (DYRK1A), Dlg-1 (DLG1), Cdc42 (CDC42), Fmr1 (FMR1, FXR1/2), trio (TRIO), Nedd4 (NEDD4L/NEDD4) and CamKII (CAMK2A/B/D) have been linked to intellectual disability." (PMID 37759179, 2023). "To date, no prior report has documented the association between an X-linked recessive FMR1 variant and an autosomal dominant KMT2C variant in autism and intellectual disability." (PMID 38025430, 2023). "FXS is the second most frequent type of intellectual disability (immature neurons, and thin and highly branched dendritic spines) that is caused by the CGG sequence repeats in the promoter region of the FMR1 gene (fragile X mental retardation 1)." (PMID 35686011, 2022). "FXR1 on the other hand is an RNA-binding protein and ortholog of the fragile X and mental retardation gene FMR1." (PMID 35666183, 2022). "FMRP is an important regulator of activity-dependent plasticity in the brain, and the mutation in the FMR1 gene and subsequent loss of its protein product lead to Fragile X Syndrome (FXS), an inherited cause of autism and intellectual disability." (PMID 36292945, 2022). "Previous metabolic and genetic investigations, including extensive metabolic screening, chromosome analysis, array CGH, Fragile X Syndrome testing (FMR1), intellectual disability panel, and trio ES, had returned normal results." (PMID 36393831, 2022). "FXS is one of the most common forms of inherited intellectual disability and is caused by an expansion of CGG-repeats in the fragile X mental retardation 1 gene (FMR1), resulting in the loss of its product, fragile X mental retardation 1 protein (FMRP)." (PMID 35163142, 2022). "The fragile X mental retardation (FMR1) gene contains an expansion-prone CGG repeat within its 5′ UTR." (PMID 35729184, 2022). "Over 100 X-linked intellectual disability genes have been identified, with triplet repeat expansions at the FMR1 (FRAXA) and AFF2 (FRAXE) genes being the causative agent in two of them." (PMID 34282157, 2021). "This is in agreement with the recent observation of an increased H+ leak in neurons from fragile X mental retardation 1 (Fmr1)-knockout mice, a model of intellectual disability." (PMID 33983919, 2021).
Intellectual disability (continued). "Re-evaluation of affected individuals within the family in which FMR1CRE is segregating revealed no clinical features suggestive of a Fragile X (FRAX) syndrome diagnosis (OMIM #300624]; FMR1 silencing) other than macrocephaly and intellectual disability." (PMID 34388204, 2021). "We conclude that clinical tests for potentially FMR1-related indications such as intellectual disability should include methods capable of detecting small coding, noncoding, and copy number variants." (PMID 34828275, 2021). "A micro-array-based comparative genomic hybridization test (array CGH test) was shown to be normal, a screen of an intellectual disability panel of 275 genes was normal, and the FMR1 gene was also normal." (PMID 34067418, 2021). "The fragile X mental retardation (FMR1) gene consists of 17 exons spanning approximately 38 kb of genomic DNA." (PMID 32632326, 2020). "Fragile X syndrome (FXS) is the leading inherited monogenic cause of intellectual disability, resulting from >200 CGG trinucleotide repeat expansions in the 5′ untranslated region of the Fragile X Mental Retardation 1 Gene (FMR1)." (PMID 30654486, 2019). "The hippocampus and amygdala were also suggested to be involved in generation of audiogenic seizures in Fragile X mental retardation 1 (Fmr1) knockout mice." (PMID 30813600, 2019). "Males carrying more than 200 repeats (an FMR1 “full mutation”) are almost always affected with FXS, exhibiting developmental delay and intellectual disability." (PMID 31694075, 2019). "Fragile X syndrome (FXS) is a common cause of intellectual disability and autism spectrum disorder (ASD) usually associated with a CGG expansion, termed full mutation (FM: CGG ≥ 200), increased DNA methylation of the FMR1 promoter and silencing of the gene." (PMID 31878865, 2019). "Fragile X syndrome (OMIM #300624), the most common inherited cause of intellectual disability and autism, is caused by expansions of a CGG repeat in the 5′ untranslated region of the gene encoding fragile X mental retardation 1 (FMR1) on the X chromosome." (PMID 29946432, 2018). "The two males identified with hypermethylation at FMR1 had phenotypes consistent with a diagnosis of fragile X, primarily intellectual disability (ID) and behavioral anomalies." (PMID 29802345, 2018). "X‐Fra syndrome is the second major cause of intellectual disability, which is caused by the expansion of CGG trinucleotide repeats in the FMR1 gene located on chromosome X and that encodes FMRP." (PMID 29934975, 2018). "DNA from dried blood spots of 151 individuals with intellectual disability or autism spectrum disorder were screened for the presence of an expanded FMR1 CGG repeat using the FMR1 TP-PCR MCA assay." (PMID 30538724, 2018). "Mutations in several genes encoding regulators of mRNA translation (i.e. FMR1) and protein degradation (i.e. UBE3A) have been associated with an increased risk for autism spectrum disorders and intellectual disability (ASD/ID)." (PMID 27365114, 2016). "CGG expansion of exon 1 of the FMR1 gene (the X-linked gene encoding FMRP) results in fragile X syndrome (FXS), the leading cause of inherited intellectual disability and monogenetic autism." (PMID 27957526, 2016). "It is also noteworthy that EHMT targets include fly orthologs of NF1, FMR1, FMR2, CNTNAP2, GDI, DLG3, and of many more genes underlying syndromic and non-syndromic forms of intellectual disability." (PMID 21245904, 2011). "The loss of the FMR1 gene product, FMRP, leads to mental retardation in males and to a range of deficits in heterozygous females." (PMID 20804589, 2010). "Fragile X syndrome (FRAXA), caused by the expansion of CGG repeats in the 5’ untranslated region of the fragile X mental retardation 1 (FMR1) gene is one of the most common forms of mental retardation." (PMID 21836667, 2010).
Intellectual disability (continued). "We describe the generation of two fmr1 knockout alleles in zebrafish, and as such provide a new genetic model system to study FXS, a highly prevalent form of inherited mental retardation." (PMID 19936290, 2009). "FXS, the most common inherited cause of intellectual disability and leading monogenic cause of autism, results from the silencing of the Fmr1 gene and subsequent loss of its protein product, the RNA binding protein (RBP), FMRP." (PMID 39185177, 2025). "The first X- linked pedigree of intellectual disability reported by Martin and Bell in 1949 was later identified to be FXS when analyzed with the FMR1 gene DNA repeat expansion test after the discovery of the FMR1 gene in 1991." (PMID 40004478, 2025). "FXS full mutation alleles are caused by silencing of (FMR1) gene and the lack or deficiency of the FMR1 protein FMRP in males, affecting synaptic plasticity and connectivity in the developing brain leading to intellectual disability (ID) and other clinical features of FXS." (PMID 36409419, 2023). "Furthermore, they tried to correlate FMR1 methylation in blood and buccal epithelial cells with intellectual disability." (PMID 37298158, 2023). "Two previous studies investigated the correlation between clinical phenotypes (intellectual disability, anxiety, and obsessive compulsive symptoms) and molecular measures (FMR1 mRNA expression levels as indicator of methylation status in the CGG repeat size in the promoter region)." (PMID 36409419, 2023). "In addition to autism and intellectual disability, some patients have epilepsy, and the Fmr1 knockout mouse has neuronal hyperexcitability." (PMID 35327449, 2022). "Taken together our findings indicate that factors connecting DCX, COMT, and FMR1 in intellectual disability and social behavior may converge at Wnt signaling, neuron migration, and axon and dendrite morphogenesis." (PMID 35590332, 2022). "Since FXS is a common and prototypical genetic disorder associated with intellectual disability (ID) and autism spectrum disorder (ASD), a comprehensive assessment of the FMR1 DNA-RNA-protein pathway and its correlations with the neurobehavioral phenotype is a priority." (PMID 33008014, 2020). "This provides some evidence that another gene associated with a language disorder is also related to these dynamic measures (FOXP2), but not another gene identified as a common monogenic cause of intellectual disability (FMR1)." (PMID 31639257, 2020). "FXS is the most common genetic cause of intellectual disability and autism and is caused by a CGG trinucleotide repeat expansion within the fragile X mental retardation 1 (FMR1) gene that is located on the X chromosome and codes for FMRP, a major interacting protein of CYFIP proteins." (PMID 31324746, 2019). "Additionally, we tested the expression of one of the MIR222 downstream targets, FMR1, known to be involved in intellectual disability." (PMID 30567555, 2018). "Since the Fmr-1 gene was discovered in 1991, its product, the Fragile X Mental Retardation Protein (FMRP), has been a topic of major discussion in the investigation of inherited intellectual deficiencies." (PMID 26580204, 2015). "Interestingly, similar phenotypes of altered social behaviors and reduced behavioral lateralization were previously reported in other mouse models of intellectual disability such as, for example, Ophn1, Gdi1, Fmr1, motopsin, and Pten mutants." (PMID 24073232, 2013). "Hypermethylation of the fragile X mental retardation 1 gene FMR1 results in decreased expression of FMR1 protein FMRP, which is the underlying cause of Fragile X syndrome – an incurable neurological disorder characterized by mental retardation, anxiety, epileptic episodes and autism." (PMID 23548045, 2013).
Intellectual disability (continued). "Several well studied X-borne genes have an effect on general cognitive abilities, including FMR1 (fragile X syndrome) and FMR2 (FRAXE mental retardation), as well as a large number of X-linked mental retardation (MRX) syndromes that have been mapped but not cloned and characterised." (PMID 18248684, 2008). "Therefore, we proposed the new gene name “Fragile X messenger ribonucleoprotein 1”, where messenger can stand for the “M” and ribonucleoprotein for the “R” in the symbol, thus breaking any implied link to “mental retardation” and removing the need for a change to the established FMR1 symbol." (PMID 35741066, 2022). "NOS abnormal expression observed in the Fmr1-KO mouse brain leads to changes in the NO metabolism, protein nitration, and NF-κB activation that may be involved in the pathogenesis of intellectual disability in the FXS and may represent a new therapeutic target for this rare disorder." (PMID 26788253, 2016). "Women with a FMR1 PM thus offer a robust model to study phenotypic profiles (including subtle AU-related traits) potentially linked to variations in the FMR1 gene, without confounding factors of intellectual disability, developmental delays, and comorbidities common in FXS." (PMID 40141125, 2025). "FMR1 molecular testing, SNP-array, screening for Angelman/Prader–Willi syndrome by MS-MLPA, targeted NGS for intellectual disability/autism spectrum disorder and hypogonadal hypogonadism, metabolic profile gave negative or normal results." (PMID 36469137, 2023). "Quantitative analysis showed increased expression of all examined genes with the most significant changes for known intellectual disability genes CAMK2A and FMR1." (PMID 34946860, 2021). "Recapitulating the intellectual disability in human FXS patients, Fmr1 KO mice display deficits in various learning and memory tasks including the hippocampus-dependent passive avoidance memory." (PMID 33297570, 2020). "These mice express a null form of the Fmr1 gene to model the genetic defect in FXS, a syndromic form of autism and the most common inherited form of intellectual disability." (PMID 29346381, 2018). "Deficits in working and episodic memory in Fmr1 KO mice are consistent with the clinical picture in FXS, in which intellectual disability is commonly seen." (PMID 28451631, 2017). "When a fully mutated FMR1 gene (>200 CGG repeats) is present, intellectual disability is observed; however, it does not affect female ovarian function." (PMID 40244008, 2025). "The Fragile Mental Retardation 1 locus (FMR1) is located on the X chromosome, and an expansion of triplet repeats preventing the proper production of the FMRP RNA-binding protein is the most common inherited pattern of mental retardation." (PMID 38534343, 2024). "Simultaneous deletion of both FMR1 and AFF2 in males results in severe intellectual disability." (PMID 30264515, 2018). "The early transcription of fmr1 gene and brain distribution of FMR1-mRNAs in human fetuses suggest that alterations of fmr1 gene expression in BFCS may be responsible for FXS typical executive and cognitive dysfunctions, and intellectual disability." (PMID 34760921, 2021). "Thus, the absence of FMR1 protein, through mechanisms not yet known, typically presents with intellectual disability, combined with dysmorphia (long face, hyperextensible joints, and prominent ears) and post-pubertal macroorchidism." (PMID 30794581, 2019).